DDX3X (DEAD-box helicase 3 X-linked)
Diseases named in the same sentence as DDX3X in open-access papers (continued):
Sharing a sentence is not in itself a finding about the gene and the disease.
tumor (continued). "The downregulation may in part result from the epigenetic modification that DDX3X promoter methylation was obviously observed in tumor samples compared with normal tissues (yellow asterisk symbols)." (PMID 32326089, 2020). "DDX3X expression is higher in normal tissues as compared with the tumor samples." (PMID 32326089, 2020). "Thus, the exact function of DDX3X is determined by its interacting targets and is tumor- and/or context-dependent." (PMID 32326089, 2020). "It is worth mentioning that despite we observe DDX3X aggregates resembling SGs in MB and other tumor types, it remains to be determined whether these structures reflect an accumulation of SGs." (PMID 27180681, 2016). "The immunogenic protein DDX3X is shown in high quantity in CD133-expressing tumor cells." (PMID 26184164, 2015). "Moreover, DDX3X level was also higher in WHO grade III (n = 19) than in non-tumor controls (p = 2.43 × 10−5)." (PMID 26184164, 2015). "While definitive evidence for the tumor-suppressive role of Ddx3X was not established, the researchers suggested that the mutations in Ddx3X could further reduce global protein synthesis mediated by MYC." (PMID 38993792, 2024). "However, DDX3X has been classified as both a tumour suppressor and an oncogene." (PMID 38057330, 2023). "Furthermore, we provide evidence suggesting that Kindlin-2 functions in this process through association with DDX3X, which facilitates DDX3X interaction with c-Myc mRNA 5'UTR and thereby promotes c-Myc translation and consequently tumor cell glycolysis and PDAC progression." (PMID 37649609, 2023). "Thus, elucidating the precise mechanism whereby these genomic variations in DDX3X interfere with the normal function of this helicase in each individual tumor type and how they contribute to tumorigenesis remains to be determined but is only of growing importance." (PMID 27180681, 2016). "Meanwhile, DDX3X expression was positively correlated with LINC00908 expression, and it also plays an important role in tumor progression for PRAD." (PMID 40344383, 2025). "To determine the protein expression levels of DDX3X in HCC, we compared its expression in 20 pairs of HCC tumor tissues to adjacent non-tumor tissues." (PMID 41198618, 2025). "Depletion of DDX3X inhibits protein synthesis, consistent with the observed translation repression after ceftriaxone and RK‐33 treatment of MYCN‐amplified tumor cells in our study." (PMID 37975412, 2024). "Top neoantigen targets for SHH included DDX3X, PRKAR1A, and PTCH1 which are genes commonly involved in tumor progression." (PMID 39160595, 2024). "DDX3X knockdown markedly suppressed the proliferation, invasion and migration of PDAC cells in vitro and inhibited tumor growth in vivo." (PMID 38316768, 2024). "Although DDX3X overexpression significantly promoted PDAC proliferation, the tumor-promoting effects were partly counteracted by SIRT7 suppression in the subcutaneous xenograft model." (PMID 38316768, 2024). "Downregulation of DDX3X enhanced proliferation, migration and invasion of CRC cells in vitro and enhanced tumor metastasis in vivo by inhibiting E-cadherin and activating β-catenin signaling via suppressing the MAPK pathway." (PMID 38023215, 2023). "The cellular enzymes DDX3X and DDX5 play important roles in the maintenance of normal cell metabolism, but their deregulation can accelerate tumor transformation." (PMID 35954483, 2022). "The downregulation of DDX3X suppresses E-cadherin expression by MDM2/Slug pathway expression and promotes tumor metastasis." (PMID 35954483, 2022). "The most prominent of these are candidate tumour suppressors; KDM6A (lysine demethylase 6 A), DDX3X (dead-box RNA helicase 3) and UBA1." (PMID 31772231, 2019). "Likewise, other genes reported to be important for HCV replication in vitro, such as cyclophilin A, phosphatidylinositol 4-kinase (PI4KIII)-α, and DEAD-box helicase 3, X-linked (DDX3X), were not differentially expressed between the tumor and the nontumorous tissue." (PMID 29538454, 2018).
tumor (continued). "This up-regulation expands to other potential tumor markers including A1AT1, tropomyosin-4, TUBB3, ACTN4, DDX3X, LMNB1, PARP and vimentin." (PMID 29109428, 2017). "It is thus likely that DDX3Y compensates the loss of DDX3X and suggests that DDX3 proteins are required for malignant transformation and are not tumor suppressors." (PMID 40772229, 2025). "The overexpression of DDX3X resulted in the upregulation of CD274 mRNA expression and consequently increased PD-L1 expression, which is known to facilitate immune evasion by various tumor cells." (PMID 38316768, 2024). "The authors conclude that tumor environmental factors such as hypoxia and nutrient deprivation activate HIF1A signaling for the maturation of AEP, which, in turn, cleaves DDX3X to promote its sequestration in the nucleus, thus initiating a nuclear DDX3X/hnRNPA1–dependent AS program in tumor cells." (PMID 38299588, 2024). "Collectively, ceftriaxone could inhibit translation via targeting DDX3X, and concomitant inhibition of MYCN overexpression by drug treatment resulted in a significant repression of translation in MYCN‐amplified tumor cells." (PMID 37975412, 2024). "Our results for tumor weight and volume suggest that stable DDX3X overexpression promotes tumor growth compared to that in the control group, while SIRT7 knockdown suppressed the tumor growth-promoting effects of DDX3X overexpression on tumor formation." (PMID 38316768, 2024). "We showed that MYCN‐amplified tumor cells had higher levels of DDX3X expression than MYCN‐nonamplified tumor cells." (PMID 37975412, 2024). "For instance, DDX3X and DDX58 could function as both tumor-promoting and tumor-suppressing roles based on different molecular pathways." (PMID 38023215, 2023). "However, we observed that DDX3X and DDX58 exert both tumor-promoting and tumor-suppressing roles in CRC." (PMID 38023215, 2023). "However, while DDX5 acts as an oncogene, thus presumably enhancing the tumor transformation function of MATR3, DDX3X can act both as an oncogene and as an oncosuppressor." (PMID 35954483, 2022). "DDX3X was found to form a complex with the cap-binding complex CBC and eIF3 to promote the transcription of ATF4, a potent activator of the epithelial–mesenchymal transformation that facilitates tumor metastasis." (PMID 35954483, 2022). "As for DDX3X, several DDX5 unique interactors were associated with different tumor types, but again there was a lack of information about the functional significance of these interactions." (PMID 35954483, 2022). "Since in this type of tumor the positive or negative role of DDX3X is not completely clear, the possible connection with these proteins remains elusive." (PMID 35954483, 2022). "In response to hypoxia, DDX3X is overexpressed in the immortalized breast epithelial cell line MCF10A, and as a consequence, it reduces the expression of E-cadherin via the Rac1-mediated signaling pathway and promotes tumor metastasis." (PMID 35954483, 2022). "Since the survival of Daudi cells depends on DDX3Y overexpression because DDX3X expression is undetectable, these results suggest RK-33 is also effective in blocking DDX3Y to slow down tumor progression and that inhibition of both DDX3 paralogues can contribute to tumor suppression." (PMID 40772229, 2025). "We demonstrated that DDX3X, a female-biased gene in TAM-MGs and Xi-expressed in a number of human tissues, is a key modulator of IFN-stimulated genes, thereby representing a candidate genetic driver of enhanced anti-tumor immunity and better GBM outcomes in females." (PMID 38895459, 2025). "Furthermore, we observed that DDX3X is upregulated in HCC and contributes to tumor progression." (PMID 41198618, 2025).
tumor (continued). "Additionally, we assessed the impact of the DDX3X N124A site on the proliferative phenotype of tumor cells by soft agar colony formation assays, grouped as the negative control (NC), DDX3X KD, DDX3X KD/DDX3X WT res, and DDX3X KD/DDX3X N124A res groups." (PMID 37988165, 2023). "In addition, the negative correlation between tumor mutation burden (TMB) and PANRG-score was revealed by spearman’s correlation analysis and the negative correlations between TMB and DDX3X, CASP7, GSDME expression levels were also uncovered (all P < 0.005)." (PMID 37666920, 2023). "As expected, knockdown of DDX3X impaired TNBC cell proliferation, migration, and invasion, suggesting that DDX3X is an oncoprotein and KLHL29 might exert its tumor suppressive functions by inhibiting DDX3X, which is further investigated below." (PMID 37845393, 2023). "In addition, higher expression of ATRX, DDX3X, KDM5C and KDM6A was observed in female patients, indicating that tumor-suppressor genes that escape from X-inactivation may contribute to HCC sex bias." (PMID 36118521, 2022). "In gastric cancer, DDX3X binds the transcription factor YY1 (yin yang 1) with the help of the circRNA circ-CTNNB1, which results in the transactivation of YY1 and the subsequent activation of genes involved in WNT/β-catenin signalling, thereby promoting tumour progression." (PMID 33627125, 2021). "However, it is not clear whether this is the right approach; indeed, several of the published studies suggest that DDX3X is a tumor suppressor rather than an oncogene." (PMID 39062517, 2024).
infection (55 papers, 2010 to 2025). The state of being infected such as from the introduction of a foreign agent such as serum, vaccine, antigenic substance or organism. "Histological analysis of infected lungs harvested on day 5 after infection suggested that the loss of DDX3X in the myeloid compartment led to a greater extent of virus spread in the lung." (PMID 33766561, 2021). "An approximate of 75% of the genes that transcriptionally altered upon the infection of the male wild-type macrophages, was responded to the infection in the DDX3X deficient counterparts." (PMID 33297945, 2020). "On the other hand, none of the altered genes in the female wild-type macrophages, were induced upon the infection in the female DDX3X deficient macrophages." (PMID 33297945, 2020). "DDX3X-deficient cells from both sexes contained higher bacterial loads compared to the wild-type cells 8 hours after infection." (PMID 30475900, 2018). "On the one hand this may result from the fact that male mice had to be used for infection experiments, hence from the weaker impact of DDX3X deficiency in cells expressing DDX3Y." (PMID 30475900, 2018). "The results showed that knockdown of DDX3X significantly restricted infection by all these RV strains." (PMID 41323147, 2025). "During the infection cycles of these pathogens, DDX3X directly facilitates viral replication and particle assembly by interacting with viral RNA and structural proteins." (PMID 40606174, 2025). "Mechanistic studies demonstrate that the DENV capsid protein interacts with the amino acid residues 223–350 of DDX3X via its N-terminal domain, downregulating DDX3X expression in late infection to achieve immune evasion." (PMID 40606174, 2025). "The interaction between the DENV capsid protein and DDX3X downregulates the expression of DDX3X in the late stage of infection." (PMID 40606174, 2025). "The levels of mRNA and protein expression for DDX3X increased significantly in virus-infected cells at different time points post-infection, along with the replication of both PRRSV Ch-1R and SD16 strains in a dose-dependent manner." (PMID 39155369, 2024). "As anticipated, all viral intermediates, including A-, B- and C-nuclear capsids, perinuclear virions and cytoplasmic capsids as well as mature extracellular virions were detectable during a wild-type infection in the presence of normal levels of DDX3X." (PMID 36725983, 2023). "As expected, DDX3X was essentially cytoplasmic in uninfected cells and partially redirected to the nucleus by the virus late in infection." (PMID 36725983, 2023). "Early in infection, an interaction with the HCV RNA 3′UTR causes DDX3X accumulation in SGs with IKKα, Ras GTPase-activating protein-binding protein 1 (G3BP1), and PABP, which leads to IKKα activation and downstream activation of lipogenesis." (PMID 36393867, 2022). "DDX3X is critical to orchestrate a multilayer antiviral innate response during infection, coordinating the activation of the inflammasome, assembly of stress granules, and type I interferon (IFN) responses." (PMID 35664076, 2022). "Further influencing DDX3Xs role in innate immune defense is the host/virus interplay, which is particularly pertinent given the vast number of viruses that block or hijack DDX3X function during infection." (PMID 36110852, 2022). "DDX3X interacts with hepatitis C virus 3’ untranslated regions and facilitates viral assembly/infection.DDX3X interacts with hepatitis C virus core protein, but the importance for replication is contentious." (PMID 36110852, 2022). "Overall, HIV-1 appears to target DDX3X throughout infection to mediate various processes essential for the viral life cycle, employing its RNA helicase activity, interactions with eIFs, and possibly its propensity to form phase-separated RNP granules." (PMID 36393867, 2022). "In SARS-CoV-2 infection, the DDX3X protein levels are upregulated during infection suggesting its involvement in the cellular response against the virus." (PMID 35664076, 2022).
infection (continued). "DDX3X primarily engaged assembly of SGs upon IAV–ΔNS1 infection and promoted NLRP3 inflammasome activation in response to NS1-expressing IAV, suggesting a mutually exclusive behavior of these host innate responses." (PMID 33766561, 2021). "We next analyzed the subcellular localization dynamics of NLRP11 and DDX3X during infection with SeV by indirect immunofluorescence microscopy." (PMID 34054816, 2021). "Starting at 4 h post infection, we observed increased expression levels and co-immunoprecipitation of endogenous DDX3X with NLRP11-eGFP in HEK293 cells that was strongest at 6 h and 16 h post infection." (PMID 34054816, 2021). "Co-localization of DDX3X and NLRP11-eGFP was also observed in HeLa-NLRP11-eGFP cells, where NLRP11-eGFP continued to stably co-localize with DDX3X over the course of 16 h of infection in the majority of cells." (PMID 34054816, 2021). "Ddx3x and Nfat5 have been reported to regulate the immune responses during pathogen infection in humans and mice." (PMID 33061243, 2020). "That this is key to DDX3X’s antiviral role was indicated by enhanced infection by human parainfluenza virus-3 (hPIV-3)/elevated virus production when the DDX3X NES was inactivated." (PMID 31575075, 2019). "Understanding the link between DDX3X subcellular localization and the host- and pathogen-directed roles of DDX3X are central to unlocking novel strategies to target DDX3X activity in infection." (PMID 31575075, 2019). "The data suggest a contribution of DDX3X to sex-specific gene expression in response to infection with Lm." (PMID 30475900, 2018). "To further characterize the role of DDX3X in immune responses, we subjected Ddx3xfl/y Vav-iCre mice to intraperitoneal (i.p.)infection with the intracellular bacterial pathogen Listeria monocytogenes (Lm)." (PMID 30475900, 2018). "We observed a significant reduction in the mRNA levels of DDX3X at 48 h pi suggesting that DENV infection suppresses the expression of DDX3X at mRNA level at later stages of infection." (PMID 29387631, 2017). "Additionally, overexpressing DDX3X also significantly increased SA11 or MSLH14 RV strain infections at 24 hpi in terms of both gene levels and virus titers." (PMID 41323147, 2025). "Infection triggers DDX3X downregulation and relocalization from neuronal somata into axons, where it interacts with microtubule-associated proteins, including the anterograde motor KIF1A, to directly facilitate viral particle transport towards synaptic terminals." (PMID 40606174, 2025). "Furthermore, our study found that the mRNA level of DDX3X was also significantly downregulated in DF-1 cells 48 h after DTMUV infection, and multiple studies have shown that DDX3X inhibits DTMUV replication in both BHK-21 and DEF cells." (PMID 39772141, 2024). "Indeed, an infection with a pUL31 deletion mutant virus recruited significantly less DDX3X to the nuclear membranes." (PMID 36725983, 2023). "Kesavardhana and colleagues assessed the antiviral function of DDX3X during IvA infection and reported that the host protein DDX3X in interplay with NLRP3 inflammasome plays a crucial role in organizing a multifaceted antiviral innate response during IvA infection." (PMID 37773712, 2023). "We hypothesized that DDX3X might recruit a key protein onto the viral particles during their budding that is needed for the subsequent stage of the infection." (PMID 36725983, 2023). "The fact that the immunopurified complexes were harvested 24 h post-infection may also imply that the N protein has already undergone phase separation to form viable “viral factories” that can interact with DDX3X, facilitating immune evasion and suppression." (PMID 35897696, 2022). "For example, HCV influences the cellular distribution of DDX3X over the course of infection." (PMID 36393867, 2022). "DDX3X also binds to the HCV core protein which associates with lipid droplets essential for infectious HCV production, however the role of this interaction in infection is contentious." (PMID 36110852, 2022).